SAA1 (serum amyloid A1)
Diseases named in the same sentence as SAA1 in open-access papers (continued):
Sharing a sentence is not in itself a finding about the gene and the disease.
infection (continued). "The established antibacterial activities of human SAA1, including binding to outer membrane protein A and opsonizing the invading bacteria for phagocytosis, also facilitate the elimination of bacteria, thus promoting the resolution of inflammatory response to infection." (PMID 39940756, 2025). "Saa1 and Slpi, significantly upregulated during infection and associated with the immune response, have not been reported in hvKp infections and could be important targets for subsequent studies." (PMID 35573776, 2022). "We cannot exclude that the binding interplay between Mtb and SAA1 is one of the host mechanisms facilitating the interaction of macrophages with tubercle bacilli, which the goal of successfully engulfing the pathogen and developing an appropriate complex immune response able to fight the infection." (PMID 34065319, 2021). "Because increased proinflammatory cytokine production may be present in intrauterine milieus in both infection- and non–infection-induced labor, we suppose proinflammatory cytokines are the upstream inducers of SAA1 expression in the placenta in both sterile and infectious labor process." (PMID 32582166, 2020). "Since IL-1β and SAA1 enhance each other’s production, we propose that a feed-forward mechanism in terms of IL-1β and SAA1 synthesis may exist in the amnion in both normal and infection-induced labor." (PMID 28386088, 2017). "Increased expression of several acute-phase reactants, such as amyloid A proteins (Saa1, Saa2, Saa3), amyloid P component serum (Apcs), haptoglobin (Hp), hemopexin (Hpx) and orosomucoid 2 (Orm2), was observed only in CerS2-null mice after transfer of iNKT cells and infection with LCMV." (PMID 29163475, 2017). "Of the 9 TN-specific proteins, 6 proteins (CRP, LBP, LRG1, SAA1, TFRC) overlapped with the WT group identifying them as infection-specific and toxin-independent proteins (black text)." (PMID 41326716, 2026). "Proteins like CRP, SERPINA3,SAA1, SAA2, and immunoglobulins were previously related to SARS-CoV-2infection in the literature,−, and their abundance increasesduring the infection and returns to their normal status after 3–4weeks postinfection." (PMID 40997940, 2025). "Disruptions in lipoproteins, cholesterol, and fatty acids observedduring severe infection were significantly restored during the postinfectionstage, as well as severity marker proteins such as CRP, SAA1, andSERPINA3." (PMID 40997940, 2025). "Serum amyloid A proteins, specifically SAA1 and SAA2, significantly upregulated during the infection phase." (PMID 40568583, 2025). "During infection, acute-phase proteins such as CRP and SAA1 leak into the alveolar space due to increased pulmonary vascular permeability." (PMID 40572197, 2025). "We also examined the expression of serum amyloid A1 (SAA1), a major acute phase reactant typically upregulated in response to tissue injury and infection." (PMID 40565363, 2025). "SAA1 and SAA2 are released into blood stimulated by IL-6 in response to infection, inflammation, injury, or stress." (PMID 40283676, 2025). "As expected, we found that their levels were similar (SAA1 and SAA2) or increased (CRP) to a greater extent in patients with more severe infection symptoms (NIH-2 group) during infection compared to those with mild to moderate characteristics (NIH-1 group)." (PMID 39183264, 2024). "Both Saa1, which is associated with lipopolysaccharide (LPS) that elicits host inflammatory response, and Slpi, which encodes an antimicrobial protein, have not previously been reported in hvKp infections and could be important targets for subsequent studies." (PMID 35573776, 2022). "In a previous proteomic study, we evaluated the expression of the different isoforms (SAA1 and SAA2) as predictors of infection development." (PMID 34200779, 2021). "Serum amyloid A1 (SAA1) is a prototypic acute phase protein, induced to extremely high levels by physical insults, including inflammation and infection." (PMID 29915572, 2018).
infection (continued). "Serum amyloid A1 (SAA1) is an acute response protein, which is mainly produced by the liver, during infection." (PMID 28386088, 2017). "Results presented here demonstrate that SAA1/2, and to a lesser extent SAA3, are induced both locally within the bladder and systemically in response to infection with UPEC." (PMID 22427910, 2012). "It is reported that two members of which (SAA1 and SAA2) are (along with CRP) the most prominent members of the acute phase response (APR) during which their serum levels rise dramatically after trauma, infection and other stimulation." (PMID 38243232, 2024). "Here, using global transcriptomics analyses, we evaluated the functional response of human MDMs, isolated from the blood of healthy donors under elevated SAA-1 conditions and during infection with nonopsonized and SAA1-opsonized tubercle bacilli." (PMID 37781389, 2023). "Overall, the differential expression of MPHOSPH8, MIR31HG, SAA1 and TRIML2 could show us the subtle changes that occur in the infection between M.BCG and P.BCG." (PMID 35562916, 2022). "We found that SAA1 expression was significantly increased in the placenta villous tissue in normal spontaneous deliveries without infection at term compared with elective c section without labor at term." (PMID 35990700, 2022). "Contrary to tubercle bacilli preincubated with SAA1, the nonopsonized bacteria replicated significantly only during the first 3 days of infection of human macrophages (day 0/day 3: Mtb 1.24 × 106/2.11 × 106 CFU/mL, p = 0.003)." (PMID 34065319, 2021). "We found that the interaction of Mtb with the physiological concentration of SAA1 prior to the infection of human macrophages did not affect the pathogen invasion of the target phagocytes." (PMID 34065319, 2021). "SAA1 and SAA2 expression levels are increased with infection, inflammation, and injury." (PMID 31188831, 2019). "Further PRM analyses were performed on the same 20 patients in order to evaluate whether either of the acute phase isoforms (SAA1 and SAA2) had a more significant effect on infection and inflammatory processes." (PMID 28701906, 2017). "In the increased proteins, serum amyloid A1 (SAA-1) and serum amyloid A2 (SAA-2) are acute phase lipoproteins rapidly produced in the liver with trauma or infection, and the serum amyloid proteins potently enhance cytokine production from peripheral blood mononuclear cells." (PMID 23763817, 2013). "Given parturition being a process of inflammation of gestational tissues and the important role of LPS, IL-1β, and SAA1 in infection and noninfection-induced inflammatory reaction, our findings may be fitted into both normal and infection-induced parturition." (PMID 36206855, 2022). "In our study, both IL-6 and SAA1 levels in sera of uninfected rhesus macaques were undetectable, whereas MTB infection resulted in a dose-dependent increase of these proteins, making these proteins sensitive markers of infection which can be detected by UCP-LFAs." (PMID 34943175, 2021). "Serum amyloid A1 may participate in parturition in the presence and absence of infection by inducing the expression of inflammatory genes in the placenta." (PMID 32582166, 2020). "Serum amyloid A1 released by the placenta may participate in the onset of labor in the presence or absence of infection by stimulating the expression of parturition-pertinent inflammatory factors with consequently increased production of proinflammatory cytokines and PGF2α in the placenta." (PMID 32582166, 2020). "The FFGHGAEDSLADQAANEWGR peptide, unique to SAA1, and the tryptic SAA2 GPGGAWAAEVISNAR peptide appeared to be significantly more abundant in patients suffering from an infection than in patients without one." (PMID 28701906, 2017).
cancer (76 papers, 2011 to 2026). A tumor composed of atypical neoplastic, often pleomorphic cells that invade other tissues. "SAA1 levels were also found to be positively correlated with unfavorable TNM stages closely linked with cancer progression and poor prognosis." (PMID 35610567, 2022). "SAA1 is an acute-phase high-density lipoprotein-associated apolipoprotein that is significantly upregulated in injury, inflammation, and cancer." (PMID 33968297, 2021). "In patients with prostate cancer, gastric cancer, lung cancer, breast cancer, endometrial cancer, esophageal cancer and melanoma, the high expression of serum SAA1 levels have been shown to be associated with poor prognosis and cancer aggressiveness 9-15." (PMID 33854635, 2021). "SAA1 is highly expressed in cancer-associated fibroblasts (CAFs), and the higher the expression of SAA1 in the matrix composition, the worse the prognosis." (PMID 31632196, 2019). "Moreover, SAA1 polymorphisms have been reported as risk factors in certain inflammatory diseases, and different variants of SAA1 play different roles in cancer." (PMID 38446289, 2024). "SAA1 is also associated with skeletal muscle wasting in cancer cachexia in mice." (PMID 38533529, 2024). "Further, it has long been suspected that SAA1 might be a prognostic marker and predictor of cancer risk." (PMID 30867991, 2019). "The expressed SAA1 then upregulates MMP-9 in macrophages to facilitate the invasion of cancer cells." (PMID 39940756, 2025). "Subsequent in vitro and in vivo experiments demonstrated that SAA1 promotes cancer cell proliferation, migration, and invasion." (PMID 41029721, 2025). "After analyzing the top genes of this cluster, the top oncogenes LCN2 and SAA1 were found which were consistent with the findings of Chen’s work and both of them were confirmed to contribute to the progression of malignant tumors." (PMID 38880903, 2024). "The loss- and gain-of-function experiments indicated that SAA1 promoted the proliferation and migration, and inhibited apoptosis of ESCC cells in vitro, consistent with previous reports in other cancers." (PMID 38446289, 2024). "Elevated levels of SAA1 have been observed in certain types of cancers and are considered a potential biomarker for cancer progression and prognosis." (PMID 38951896, 2024). "PLOD2 + SAA1 + cancer cells with intricate crosstalk patterns indeed show promise for potential therapeutic interventions." (PMID 38951896, 2024). "Previous studies have shown that SAA1 is involved in the apoptosis, migration, invasion and metastasis of a variety of cancer cells." (PMID 38446289, 2024). "Clear downregulation of certain proteins (CRP, SAA1) which reflect inflammation and cancer risks was observed." (PMID 36979008, 2023). "CAA promotes the malignant characteristics of cancer through the expression of SAA1, suggesting that SAA1 is a new therapeutic target for cancer." (PMID 37305043, 2023). "Flow cytometry experiments demonstrate the dispensable roles of SAA1-2 in cancer-dependent neutrophil infiltration to the liver." (PMID 36817472, 2023). "It has been found that the higher expression of SAA1 predicts advances and malignancies in various cancers." (PMID 37063864, 2023). "Taken together, we established mice where we completely canceled cancer-dependent increase in SAA1-2 proteins in the liver, allowing us to investigate the in vivo significance of these proteins in cancer-induced liver inflammation." (PMID 36817472, 2023). "In this regard, investigating SAA1-2 in other cancer models is critical to deepening our understanding of how SAA1-2 proteins contribute to specific pathophysiology in vivo." (PMID 36817472, 2023). "4T1 cancers elevate the expression of SAA1 and SAA2, the two major murine acute phase proteins in the liver." (PMID 36817472, 2023). "In CPTAC-ccRCC, the protein expression of genes AR, GNB3, HHLA2, LIMCH1, and SAA1 had statistical significance in some comparisons of normal samples and cancer stage (Figure A9a–e)." (PMID 35565241, 2022).
cancer (continued). "Involved in the production of nitric oxide and other reactive oxygen elements, SAA1 seems to have a role in proliferation, migration, and invasion of cancer cells, including GBM cells." (PMID 35216175, 2022). "SAA1 is a member of the serum amyloid A family of apolipoproteins, which play an important role in chronic inflammation, cancer and other diseases." (PMID 36605443, 2022). "When the body suffers from inflammation, trauma, surgery or advanced malignant tumors, the expression of SAA1 is significantly up-regulated." (PMID 34084746, 2021). "By analyzing three public cancer datasets, we found two intersection genes, SAA1 and CCL20, in these three datasets." (PMID 34084746, 2021). "Plasma levels of SAA1 are elevated following injury, inflammation, and brain trauma, as well as cancer." (PMID 29603594, 2018). "Our data confirm plasma SAA1, PIGR, SPP24, FASN, and possibly THBS1 as potential biomarkers that are common to different types of malignant tumours and associated with Abnormal Savda." (PMID 25652121, 2015). "Apart from IL8, the co-regulation between NF-κB and AP1, CEBPB or STAT3 for genes IL1B, ICAM1, IL6, PTGS2, and SAA1 in the TF regulatory networks is consistent with previous observation in HNSCC or other cancer cells." (PMID 24069219, 2013). "Functionally, SAA1 promoted cancer cell proliferation, migration, and invasion." (PMID 41029721, 2025). "In addition, cancer cell–derived SAA1 promotes the recruitment of MDSCs and their differentiation from GMPs via TLR2/4 signaling, while also inducing IL-1β secretion by MDSCs." (PMID 41029721, 2025). "However, few of these studies directly address the mechanisms by which SAA1 promote the progression of cancer." (PMID 38446289, 2024). "Moreover, the results of the transwell assay showed that the knockdown of SAA1 inhibited the ccRCC cancer cell migration and invasion." (PMID 37108666, 2023). "SAA1 modulates neutrophil function in the context of cancer." (PMID 35565241, 2022). "When stratifying within the cancer patient cohort, cholesterol efflux capacity was significantly decreased in plasma samples with high SAA1 levels, indicating a physiologic relevance of SAA1-mediated HDL remodeling in PDAC." (PMID 35577388, 2022). "One cancer-associated gene (MPHOSPH8) was upregulated in samples infected with M.BCG relative to those infected with P.BCG, whereas three genes were downregulated in M.BCG (MIR31HG, SAA1, and TRIML2)." (PMID 35562916, 2022). "Therefore, further experiments are required to directly address this issue to ensure a better understanding of the interaction of LCN2 with SAA1 in cancer and to figure out the role of SAA1 in GC cells in the future." (PMID 35705840, 2022). "Despite a relatively short DSS administration period, WOL intervention improved the expression levels of cancer-related proteins in the colon (Anxa3 and Co3) as well as oncogenic hepatic genes (Saa1, Jun and S100a8) as observed in the DSSWOL mice as compared to the DSS group." (PMID 32258419, 2020). "SAA1 was first described as an inducible factor in plasma during cancers in 1993." (PMID 33063952, 2020). "Notably, 10 over-expressed genes (Comp, Mmp3, Adipoq, Angptl7, Fgg, Hp, Mstn, Saa1, Serpina3n, and Cxcl12) are translated into secreted proteins, and therefore, can be further explored as potential cancer cachexia biomarkers." (PMID 31013615, 2019). "We considered that SAA1 may negatively regulate inflammatory response and might promote the survival of cancer cells." (PMID 30867991, 2019). "In addition, LEC-released chemokines also stimulated the expression of serum amyloid A1 (SAA1) in cancer cells, enhancing their lymphatic invasion by increasing VE-cadherin phosphorylation, junction disruption, and vascular permeability of LECs." (PMID 31390756, 2019).
cancer (continued). "Inhibition of CXCR2 by SB225002 attenuated the upregulation of SAA1 by LECs co-cultured with LC cells, suggesting that LEC-derived chemokines may reciprocally activate SAA1 expression in cancer cells via CXCR2." (PMID 31390756, 2019). "SAA1 was found to be increased in skeletal muscle of cachectic mice with cancer." (PMID 24651840, 2014). "Thus, 4T1 cancer cells can reprogram the host immune system independently of SAA1-2." (PMID 36817472, 2023). "Moreover, the colocalization signals of CitFbg and SAA1/2 were enhanced in cancer patients." (PMID 37620307, 2023). "Moreover, the up-regulation of SAA1 could be used as a predictor and prognostic biomarker for a variety of malignant tumors." (PMID 37081987, 2023). "Besides, suppression of SAA1 expression can also occur after surgery or in late cancers." (PMID 35646102, 2022). "High SAA1 expression could be used as a potential biomarker for a variety of malignant tumors." (PMID 34084746, 2021). "Mechanistically, loss of PAK1 promoted mRNA decay and inhibited the expression of CD44, SAA1, MTOR, RPS6KB1, and EIF4G1, the factors involved in tumorigenesis in many cancers." (PMID 41459112, 2026). "Most of these proteins are recognized as potential prognostic biomarkers in liver (TFRC and GPLD1), renal (IGHG1, PRCP, SAA1/2, and IL1RAP) and digestive (PRSS3) cancers in the Human Protein Atlas database." (PMID 41155404, 2025). "SAA1-overexpressing or SAA1-knockdown ESCC cells were used to assess the effects of SAA1 on the proliferation, migration, apoptosis of cancer cells and the growth of xenograft tumors in nude mice." (PMID 38446289, 2024). "SAA1 and CRP are biomarkers of acute inflammation and cancer development; also, in earlier proteome analyses of BS patients, a decrease in the concentrations of both proteins was reported." (PMID 36979008, 2023). "In this study, we mined and analyzed the public cancer databases (TCGA, UALCAN and GEPIA) to conclude that SAA1 was up-regulated at mRNA and protein levels in advanced ccRCC." (PMID 34084746, 2021). "Moreover, the up-regulation of SAA1 could be used as a biomarker for a variety of malignant tumors." (PMID 34084746, 2021). "We found that the mRNA of SAA-1 and SAA-4 was much higher in cancer tissues than in adjacent tissues by qRT-PCR." (PMID 32517794, 2020). "Therefore, such increase in SAA1 could worsen muscle atrophy during cancer cachexia." (PMID 33142864, 2020). "Several proteins related to cancer development and progression were identified in the list of abundant proteins in FTC, including Ras-related protein Rab-21 (RAB21), Keratin 13 (KRT13), and Serum amyloid A1 (SAA1)." (PMID 40740986, 2025). "Furthermore, the expression of QPCTL was positively correlated with SAA1, POSTN, PLA2G2A, SAA2,C6orf15, H19, PI3, etc., whose expression also affects cancer progress." (PMID 37063864, 2023). "SAA1 is a member of the apolipoprotein serum amyloid A (SAA) family, and it is an acute phase protein secreted by the liver in response to inflammation, trauma, surgery or advanced malignant tumors." (PMID 37081987, 2023). "Furthermore, an immunohistochemical analysis of our external validation dataset was used to detect SAA1 and PDL1 expression in the ccRCC cancer tissues and corresponding normal tissues." (PMID 37108666, 2023). "It suggests that SAA1, CXCL10, CCR5, CCL19, CXCL11, CXCL13, and CCL5 have important function in immunotherapy for cancer patients, and may be used as key regulator genes of immunotherapy." (PMID 34093667, 2021). "The quantitative Reverse transcription polymerase chain reaction (qRT-PCR) assay revealed that the Messenger RNA (mRNA) of SAA-1 and SAA-4 was much higher in cancer tissues than in adjacent tissues, and MMPs was up-regulation including MMP-1, MMP-9 and MMP- 12 in OVCAR-3 cell stimulated by SAA." (PMID 32517794, 2020).